FOXP3 (forkhead box P3)
Diseases named in the same sentence as FOXP3 in open-access papers (continued):
Sharing a sentence is not in itself a finding about the gene and the disease.
Immunodeficiency (continued). "The NR4A proteins, including NR4A3, can regulate Treg development through the activation of FOXP3 and have therapeutic potential in immune disorders and cancer." (PMID 37532692, 2023). "The aim of this review is to present the role of the Foxp3 transcription factor in the human body in maintaining immune homeostasis and its significance during the development of immunodeficiency." (PMID 35207219, 2022). "The results of the GSEA showed that the top three high-FOXP3-related enrichment pathways were intestinal immune network for IgA production and immune diseases including primary immunodeficiency and allograft rejection." (PMID 34006632, 2021). "Defects in Foxp3 expression, Treg cell development, and function lead to several human immune diseases." (PMID 32117202, 2019). "CD4+CD25+FOXP3+ nTreg cells derived from thymus are known to modulate immune disorders such as autoimmunity, allergy, and graft rejection by suppressing activation of naïve T cells, effector T cells and memory CD4+ and CD8+ T cells." (PMID 31815635, 2019). "Increased TGF-β and Foxp3 at sites of inflammation was associated with elevated CD4+CD25+Foxp3+ Treg populations, which can down-regulate the progression of experimental immune disorders." (PMID 22873180, 2012). "Increased TGF-β and Foxp3 by FFO was associated with regulatory T cell populations, which can down-regulate the progression of experimental immune disorders." (PMID 22873180, 2012). "Increased Foxp3 DNA methylation levels have also been associated with exposure to Bisphenol A (BPA), with Foxp3 DNA methylation identified as a key molecular mechanism underlying BPA-induced immune dysfunction." (PMID 40244232, 2025). "The reduced expression of FOXP3 is suggested to be responsible for the decreased numbers of T-regs, which may further mediate the immune dysfunction in SSc." (PMID 38535072, 2024). "Several articles have further investigated properties of expanded Tregs from healthy persons and from immune disorders, including Crohn’s disease, and found that Tregs expanded ex vivo retain stable FOXP3 expression and even increase their suppressive capacity." (PMID 38632993, 2024). "Despite early ART initiation, the persistence of PD-1+ and CD39+ FoxP3+ CD8 T-cells could contribute to immune dysfunction and disease progression." (PMID 35967314, 2022). "FOXP3 was initially identified as an immune mediator involved in the differentiation and maturation of Tregs and has since been shown to play important roles in immune diseases." (PMID 35322929, 2022). "The monogenic immune disorder IPEX (Immunodysregulation, Polyendocrinopathy, Entereopathy, X-linked syndrome) provides an example of a breach in tolerance in which mutations in the forkhead box P3 (FOXP3) gene leads to loss of Treg and/or their function." (PMID 33936046, 2021). "Since SCFA play a critical role in controlling Treg generation and maturation, we speculated that Blend 2 alleviated inflammation and immune dysfunction by promoting a SCFA-dependent maturation of CD4+ Foxp3+T cells." (PMID 30717413, 2019). "The understanding of Foxp3 protein PTMs in modulating Treg suppression may facilitate the design of rational therapies for immune disorders developed in IPEX patients." (PMID 31681337, 2019). "Understanding Foxp3 protein features and modulation mechanisms may help in the design of rational therapies for immune diseases and cancer." (PMID 31681337, 2019). "Our analysis strengthens earlier reports of immune dysfunction in LCH by showing the abnormalities extend beyond Foxp3+ Tregs to unconventional T cell lineages that could be equally important factors in LCH." (PMID 30405183, 2018). "Since FoxP3+ Treg cells play a crucial role in suppressing immune response, the increase of FoxP3+ cells observed in HTLV-1 infection may contribute to immunodeficiency, which is frequently observed in HTLV-1 infection." (PMID 22647666, 2012).
Immunodeficiency (continued). "As FOXP3 expression may be affected by the degree of immunodeficiency, we analysed the relationship between the CD4+T cell count and the percentage of CD4+T cells expressing FOXP3." (PMID 20668701, 2010). "CD4+ T cells regulate the inflammatory environment in RA through various subsets, CD4+/CD8+ is associated with immune dysfunction, an increased CD4+/CD8+ ratio has been implicated in patients with RA, while the development and suppressive activity of Treg cells require the master regulator FOXP3." (PMID 36615560, 2023). "Moreover, CD28-CD39+ CD8 T-cells could contribute to immune dysfunction and disease progression through similar mechanisms than FoxP3+CD39+ CD8 T-cells." (PMID 35967314, 2022). "For instance, IL2 promotes the development of CD4+CD25+FoxP3+ Tregs, that represent an immunomodulatory T cell specialized subset able to neutralize the development of immune-mediated damage and to promote repair and regeneration of affected target-organs in systemic immune diseases." (PMID 33324641, 2020). "Purpurin played an anti-inflammatory role by inhibiting IL-6, TNF-α, and IL-1β and increasing IL-10, and regulated immune disorder by decreasing the CD4+/CD8+ ratio and increasing the FOXP3 level." (PMID 36615560, 2023). "The assessment of antigens related to immune regulation, such as FOXP3 and CTLA4, is also of some help, but NGS panels are increasingly adopted in subjects with immunodeficiency and lymphoproliferation." (PMID 33809703, 2021). "Under these conditions, Treg cells are readily converted to ex-Foxp3 TH17 cells, impairing immune homeostasis and exacerbating certain immune disorders." (PMID 30413714, 2018). "Our results uncovered a range of known crucial Treg regulators with relevance to several immune diseases such as IBD, along with several novel factors that are likely to play equally important roles in FOXP3 expression." (PMID 29730990, 2018). "Continuous expression of FoxP3 is needed to maintain lineage identity and function of mature Treg cells, such that attenuation or loss of FoxP3 expression leads to defective Treg suppressive function and conversion into effector cells, enhancing rather than inhibiting the immune disease state." (PMID 25339185, 2014). "Forkhead box P (FOXP) TFs—FOXP1, FOXP2, FOXP3, and FOXP4—are involved in embryonic development, immune disorders, and cancer progression, but FOXP3’s targeting of CD4 + CD25+ regulatory T (Treg) cells and its dual role as an OCG or tumor suppressor in cancers are unclear and controversial." (PMID 38827026, 2024). "In our study, immune dysfunction in the model rats, including the downregulation of the CD4/CD8 ratio, decreased in CD4+CD25+FOXP3+ Tregs and the secretion of inflammatory factors TNF-α and IFN-γ increased, which reflected a negative regulation of haematopoiesis." (PMID 35434141, 2022). "Excess FOXP3 expression leads to Treg proliferation and severe immunodeficiency, whereas lack of FOXP3 results in immune system activation and aggressive lymphoproliferation." (PMID 32222891, 2020). "The observation of significantly lower number of both CD4+ and FOXP3+ cells in the HIV‐only group compared with either of the HCV groups reflects both their immunodeficiency and absence of a hepatic pathogen." (PMID 24597693, 2014). "Here, we show that both hyperactivated CTLA-4 and FOXP3 are related to an unfavorable prognosis, and the amount of CTLA-4+ TILs is higher than FOXP3+ Tregs, which indicates that besides FOXP3+ Tregs, other CTLA-4+ TILs may be involved in antitumor immune disorders." (PMID 34526987, 2021). "FOXP3 appears to be critical for the development and function of Tregs, and the loss of FOXP3 expression leads to the lack of Tregs and hyperactivation of CD4+ T cells, resulting in lethal autoaggressive lymphoproliferation, whereas overexpression of FOXP3 results in severe immunodeficiency." (PMID 24040244, 2013).
Immunodeficiency (continued). "We found that despite decreasing frequencies of total FoxP3+ CD8 T-cells, early ART initiation failed to decrease the expansion of FoxP3+ CD8 T-cells with highly immunosuppressive functions and their potential migration to the gut, which may contribute to immune dysfunction and disease progression." (PMID 35967314, 2022). "Although early ART normalized total FoxP3+ CD8 T-cells frequencies, it did not affect the persistent elevation of the gut-homing potential of CD39+ and LAP(TGF-β1)+ FoxP3+ CD8 T-cell, which may contribute to immune dysfunction." (PMID 35967314, 2022).
multiple sclerosis (74 papers, 2008 to 2026). A progressive autoimmune disorder affecting the central nervous system resulting in demyelination. "In other previous studies, the authors studied the FOXP3 variant in male and female patients with multiple sclerosis and the authors divided the results into both groups and discussed them separately." (PMID 35905575, 2022). "Recently, our group demonstrated that -3279 C > A of FOXP3 variant was associated to multiple sclerosis diagnosis in female patients." (PMID 33686190, 2021). "Previously, our group evaluated the -3279 C > A of FOXP3 variant (rs3761548) and demonstrated that the presence of the A allele increased the chance to have multiple sclerosis diagnosis in female patients." (PMID 33686190, 2021). "The purpose of our study was to evaluate the association of chosen polymorphisms of FOXP3 gene (rs3761549, rs3761548, rs3761547) with different clinical multiple sclerosis (MS) data of our relapsing-remitting groups of patients and in control group." (PMID 30229436, 2018). "Several inflammatory diseases including multiple sclerosis and inflammatory bowel disease have been associated with dysfunctional and/or reduced numbers of Foxp3+ regulatory T cells (Treg)." (PMID 29535709, 2018). "Fletcher and colleagues reported that CD39+Foxp3+ Treg cells can suppress pathogenic Th17 cells and are impaired in cases of multiple sclerosis." (PMID 22489829, 2012). "Inflammatory environments induce the generation of dysfunctional IFNγ+T‐bet+FOXP3+ Th1‐like Tregs, which show defective function and are found in autoimmune conditions including multiple sclerosis (MS)." (PMID 39444366, 2025). "In HV, this population represents about 10% of CD4+CD25+Foxp3+T cells, and is increased in diseases such as multiple sclerosis." (PMID 36426347, 2022). "Prevotella histicola increases tolerogenic responses (including expansion of CD4+FoxP3+Tregs in the spleens and mesenteric lymph nodes of mice in which experimental autoimmune encephalitis (a model of human multiple sclerosis) is attenuated." (PMID 32574158, 2020). "Specifically, RSV effect on tolerance is likely to be in the induction of Foxp3+ T cells and IL-10 expression, which are critical to development of T cells that are protective against autoimmune diseases, such as multiple sclerosis." (PMID 26441683, 2015). "In a rat model of multiple sclerosis, IL-5 administration had therapeutic effects, acting at least in part by inducing FoxP3+ regulatory T cells." (PMID 23940537, 2013). "Active vitamin D (1,25(OH)2D) more potently induces CD4+CD25+Foxp3+ (regulatory) T cells from PBMCs of female than male subjects with multiple sclerosis." (PMID 23826346, 2013). "Impaired suppressive capacity of CD4+CD25+FOXP3+ regulatory T cells (Treg) from peripheral blood of patients with multiple sclerosis (MS) has been reported by multiple laboratories." (PMID 21437244, 2011). "The shift to CD4+CD25+Foxp3+ Treg and CD4+CD25+Foxp3+CD39+ subset plays a significant role in restricting the detrimental effect of TH17 cells in multiple sclerosis patients." (PMID 22164330, 2011). "Our objective was to study impacts of Natalizumab therapy on Foxp3+ T regulatory cells (Tregs) in multiple sclerosis (MS) patients." (PMID 18836525, 2008). "Importantly, in CD4+ T cells of multiple sclerosis patients, both Egr-1 and Foxp3 were found to decrease." (PMID 40235598, 2025). "Interestingly, a recent study demonstrated that TIGIT signaling enhances the function of FOXP3+ Tregs from patients with multiple sclerosis by upregulating Foxo1 that blocks T-bet expression and limits IFN-γ secretion." (PMID 34314385, 2021). "In addition, the administration of RSV to mice developing experimental autoimmune encephalomyelitis – an animal model of human multiple sclerosis – increases expression of IL-10 and Foxp3 in T cells, the animal model of multiple sclerosis." (PMID 26441683, 2015).
multiple sclerosis (continued). "There are some methodological concerns, about whether FOXP3 isoforms are causally associated with certain diseases: First, FOXP3 isoforms change during different stages of disease development, as shown in the studies on COPD and multiple sclerosis." (PMID 37868998, 2023). "Finally, we investigated whether CTLA‐4 signaling peptide could induce Foxp3 expression in multiple sclerosis (MS) patient PBMCs." (PMID 34306974, 2021). "Infection with helminths have been associated with increased numbers of circulating CD4+ CD25+ FoxP3+ Tregs and of autoantigen-stimulated PBLs that produce IL-10 and TGF-β, observations that have been associated with an improved clinical course in patients with multiple sclerosis." (PMID 25410903, 2014). "Using BM from nine healthy donors and five individuals with multiple sclerosis, alongside blood from healthy donors, the authors investigated the role of the BM site in maintenance of both FOXP3+ and FOXP3− regulatory CD4+ T cells." (PMID 41211791, 2025). "Our data that FoxP3 is induced by THC in SEB model is consistent with previously published studies in models such as Graft-vs-Host disease and experimental model of Multiple Sclerosis." (PMID 32612530, 2020). "In mouse models of multiple sclerosis, EAE, ERα signaling suppressed EAE development by increasing PD-1 signaling on cognate CD4+ (Foxp3-) T cells, and that inhibition of PD-1 signaling removed the estrogen dependent inhibition of EAE." (PMID 31849948, 2019). "While it was shown in patients with multiple sclerosis that fingolimod decreases the amount of circulating CD4+ T cells, the remaining CD4+ T cells were enriched with regulatory FoxP3+ cells." (PMID 29618748, 2018). "In experimental autoimmune encephalomyelitis and a murine model of multiple sclerosis (MS), the inhibition of Ang II signaling reduced the autoreactive T-cell populations while increasing the CD4+ FoxP3+ regulatory T-cells, potentially reversing the disease progression." (PMID 40722848, 2025). "In the multiple sclerosis mouse model of experimental allergic encephalomyelitis (EAE), myelin basic protein (MBP) activated human Treg cells control the expression of T-effector cells with enhanced Foxp3 expression." (PMID 35720406, 2022). "Interestingly, we also detected Foxp3− Th cells that expressed NRP1 in the target organ during experimental autoimmune encephalomyelitis (EAE), an induced mouse model of autoimmune neuroinflammatory disease that is used as an analog of human multiple sclerosis." (PMID 36069030, 2022).
COVID-19 (72 papers, 2020 to 2025). A disease caused by infection with severe acute respiratory syndrome coronavirus 2. "Firstly, Tregs and the transcription factor FoxP3 were elevated in severe COVID-19 patients, which was associated with worse outcomes." (PMID 35497875, 2022). "We performed the same analyses on Foxp3+ Tregs exclusively and found that COVID-19 was associated with hyperactivation in this population as well." (PMID 35012610, 2022). "Treg cells detected by FOXP3 staining in multi-color immunofluorescence imaging were expanded in the lymph nodes and spleens, in contrast to the loss of GCs after 2–3 weeks of COVID-19 development." (PMID 34882757, 2021). "In addition, NF-κB may also be associated with virus-related pathways, such as FOXP3 in COVID-19 (WP50630)." (PMID 35625673, 2022). "On the contrary, severe COVID-19 patients exhibit a phenotype characterized by FoxP3 expression and a higher proliferation score, along with Treg-associated parameters in the convalescent phase, which are influenced by age, sex, and severity score." (PMID 41488664, 2025). "These events collectively inhibit IL-2/STAT5-dependent Foxp3 sustenance while inducing negative regulators such as RORγt and T-bet, as evidenced by the overrepresentation of Tbet+ Tregs in severe COVID-19 patients." (PMID 40806563, 2025). "Among them, tocilizumab is an anti-IL-6R monoclonal antibody (mAb), which has demonstrated clinical efficacy as an anti-COVID-19 drug by targeting the epigenetic inheritance of FOXP3+Tregs." (PMID 39144146, 2024). "Bronchoalveolar lavage fluid samples from COVID-19 patients with ARDs have been shown to exhibit increases in FOXP3+Tregs and Th17 cells together with overall reductions in T cell numbers." (PMID 38887291, 2024). "It was indicated that patients with severe COVID-19 exhibit elevated levels of CD25+FOXP3+ Tregs within total CD4+ T cells with increased FOXP3 expression, which normalized in recovering individuals or convalescent patients." (PMID 39519310, 2024). "This was in line with the increased cytokine levels observed in severe cases of COVID-19 since FoxP3, IFNγ-R1, and STAT5+ mRNA promotor genes are involved in T cell differentiation towards Treg, Th1, Th2, and Th17, and their corresponding cytokine milieu." (PMID 37569646, 2023). "CD4+ T cells are hyperactivated in severe COVID-19 patients, although Foxp3 expression is suppressed." (PMID 36992283, 2023). "In this study, the expression level of CD4+CD25+Foxp3+ T-regs was higher in COVID-19 patients than healthy controls." (PMID 38139439, 2023). "The CD patients exposed an increased expression of anti-inflammatory molecules like CD4, CD25 (IL-2Rα), and FOXP3, compared to severe COVID-19 patients and controls." (PMID 38138121, 2023). "Decrement in percentage of CD4+FoxP3+ Tregs in peripheral blood of COVID-19 patients in terminal stage of disease is in line with lower systemic TGF-β, one of the major products of Tregs." (PMID 37057213, 2023). "A significant number of variations in the phenotypic characteristics of Tregs have been reported in severely infected patients with COVID-19, along with increased FoxP3 expression with a unique transcriptional pattern that is very similar to tumor Tregs." (PMID 36992283, 2023). "The percentage of FoxP3+ cells was significantly lowered in stage IV in comparison to stage I of COVID-19." (PMID 37057213, 2023). "To support this presumption, when correlation analysis was preformed, we found strong positive correlation between percentage of CD4+IL-10+ cells and CD4+FoxP3+ cells in peripheral blood of COVID-19 patients in IV stage." (PMID 37057213, 2023). "This study reports an increase in levels of both conventional and unconventional subtypes of Foxp3+ Tregs (cTregs/uTregs), as well as IL-35+ and IL-10+ producing Bregs, in the blood of COVID-19 patients during infection and relative to disease severity." (PMID 37833265, 2023).